MAOA (monoamine oxidase A)
Diseases named in the same sentence as MAOA in open-access papers (continued):
Sharing a sentence is not in itself a finding about the gene and the disease.
depression (continued). "Recently, evidence has indicated that the MAOA gene may associate with depression and stress." (PMID 24878765, 2014). "However, little is known about whether the MAOA uVNTR polymorphism confers vulnerability to major depressive disorder (MDD) or suicidal behavior for the Han Chinese population in Taiwan." (PMID 21605465, 2011). "BDNF rs6265 was associated with catastrophising (p = 0.044), OPRM1 rs1799971 with anxiety (p = 0.030), and MAOA rs1137070 with depression (p = 0.020)." (PMID 41460692, 2026). "Further, citropten showed antidepressant neuroprotection against chronic mild stress-induced depression in rats via raising the heat shock protein-70 expression and monoamine oxidase-A inhibitory actions." (PMID 40728987, 2025). "GG-derived geranylgeranylacetone has been shown to mitigate depression-associated behaviors in the forced swim and tail suspension tests in a chronic mild stress mouse model of depression via the suppression of monoamine oxidase-A expression." (PMID 41465559, 2025). "Biological factors contribute to depression through inflammation, HPA axis, glutamate excitotoxicity, and genetic predisposition like 5‐HTTLPR and MAOA genes." (PMID 40387308, 2025). "To further validate that BDT alleviates depression by targeting MAOA and predict bioactive components modulating this mechanism, we employed network pharmacology analysis." (PMID 41471275, 2025). "MAO-inhibitors were introduced as a remedy for depression in the 1950s and target the ability of a mitochondrial enzyme MAOA to contribute to the degradation of serotonin to its metabolic end-product 5-hydroxyindoleacetic acid (5-HIAA)." (PMID 41152544, 2025). "Studies have indicated the role of MAOA enzyme activity in the etiology of major depressive disorder (MDD) and suicidality)." (PMID 40149678, 2025). "But still, our results seem to broadly support the notion that genetic and epigenetic variation in the MAOA, and 5HTT genes influence serotonin metabolism and that serotonin metabolism affects depression." (PMID 41152544, 2025). "Specifically, SIRT1‐FOXO1 was discovered to ameliorate depression‐related phenotypes in Parkinson's disease (PD) mouse models by regulating the transcription of monoamine oxidase A (MAO‐A)." (PMID 40237232, 2025). "In depressive disorder, elevated MAOA expression and subsequent reductions in cerebral 5-HT and NE levels are recognized as key pathogenic factors." (PMID 41471275, 2025). "Research suggests that MAOA expression is increased in depression and inhibiting it can help restore healthy neurotransmitter levels and even protect neurons from cell death." (PMID 39680432, 2024). "A strong inhibition of monoamine oxidase A and α-glucosidase was observed, which indicates potential application in treatment of depression and type 2 diabetes mellitus." (PMID 39458851, 2024). "Variants within the monoamine oxidase A (MAO-A, MAOA) and tryptophan hydroxylase 2 (TPH2) genes, the main enzymes in cerebral serotonin (5-HT) turnover, affect risk for depression." (PMID 37322010, 2023). "Cerebral monoamine oxidase A (MAO-A) levels are altered in depression, as are DNA methylation levels within the MAOA gene, particularly in the promoter/exon I/intron I region." (PMID 36573644, 2023). "Animals exposed to chronic stress and patients with depression exhibit elevated MAOA activity in the brain." (PMID 37242280, 2023). "Genetic variants within the genes coding for the central monoamine-turnover proteins MAO-A (MAOA) and TPH2 (TPH2) have been linked to risk for depressive disorders and related phenomena." (PMID 37322010, 2023). "Recent research proved that high-activity of the MAOA gene can make the rapid catalyzation of 5-HT and NE, thereby leading to depression." (PMID 36032227, 2022). "A role for increased MAOA activity/expression in the pathophysiology of different forms of depression, such as major depressive disorder and postpartum depression, has been established." (PMID 34881779, 2022).
depression (continued). "Monoamine oxidases are major mechanisms by which norepinephrine, epinephrin and serotonin are degraded, and clorgyline, a specific, irreversible inhibitor of MAOA have been used in the treatment of depression for many years." (PMID 36107478, 2022). "Consistent with previous studies on major depression, our results demonstrate a remarkably increased MAOA mRNA level in the PIU group." (PMID 34335325, 2021). "The genetic variation in MAOA contributes to impulsive aggression and depression through a neurobiological mechanism." (PMID 34199135, 2021). "Polymorphic variants in SLC6A4, MAOA, DRD4, and DRD2 have shown statistical associations with major depressive disorder, anti-social behaviour, schizophrenia, and bipolar disorder." (PMID 33809805, 2021). "Depression, anxiety, and binge drinking in adolescents are associated with polymorphisms in the serotonin transporter (5-HTT) S-allele, the monoamine oxidase A (MAOA) low-activity alleles, and the dopamine D2 receptor (DDR2) Taq A1 allele." (PMID 34639443, 2021). "Since this report is an initial study on the role of miR-15b/miR-92b in MAOA activity for the development of OSA-related depression, a limitation should be acknowledged." (PMID 34829725, 2021). "Patients with depression have greatly increased brain MAOA activity providing an explanation for low synaptic levels." (PMID 40761411, 2021). "Individual compounds from flavonoids and carotenoids have been tested for mechanisms in important drug targets, MAO (MAOA and MAOB) and BDNF, which are known to be associated with depression through molecular docking studies for possible inhibitory roles." (PMID 35052561, 2021). "Converging lines of evidence from gene-by-environment studies and from DNA methylation studies have suggested that MAOA plays a role in antisocial behaviour, substance misuse, depression, and other mental disorders." (PMID 34424394, 2021). "We examined the roles of hostility and depression in the association between internet gaming disorder (IGD) and monoamine oxidase-A (MAOA) EcoRV polymorphism (rs1137070)." (PMID 34199135, 2021). "PET research further revealed higher density of MAOA in the brain of individuals with major depression than that in HCs." (PMID 34335325, 2021). "Moclobemide is known as a reversible inhibitor of monoamine oxidase A. Some studies support that monoamine oxidase inhibitors can suppress TSH levels in a fairly high percentage of depression patients." (PMID 34234669, 2021). "Higher MAOA activity can result in the rapid catalyzation of serotonin and norepinephrine, thereby contributing to depression." (PMID 34199135, 2021). "Elevated MAOA activity in the brain is found in animals exposed to chronic stress and in patients with depression." (PMID 34335325, 2021). "Only one study has examined sex differences in methylation of MAOA: The sample was small, 23 of the 66 participants presented with depression, and women showed higher methylation levels than men within the exonic region." (PMID 34424394, 2021). "This matches with the hub genes from PPI network, in which EGFR has been proved to be a significant depression-related gene, MAOA and MAOB are crucial target genes of various mental diseases, and MAOA is particularly important in depression and anxiety." (PMID 32182911, 2020). "An increase in MAOA expression results in a decrease in serotonin levels in the brain, which has been suggested as the main factor in major depressive disorder." (PMID 33584798, 2020). "The substrates of MAOA are important factors in neural signal transmission; people with an abnormal expression of MAOA exhibit phenotypes, including autism, an aggressive behavior or depression." (PMID 32426368, 2020). "A major goal of our group is to develop compounds capable of inhibiting monoamine oxidase A as a target for the treatment of depression and psychological disorders." (PMID 32431898, 2020).
depression (continued). "In conclusion, the most important bioactive components—anthraquinone, kaempferol, and vanillic acid—can alleviate depression symptoms by regulating MAOA, MAOB, and ESR1." (PMID 32182911, 2020). "Many plant polyphenols have also shown inhibitory properties against monoamine oxidase A (MAO-A), an enzyme involved in depression." (PMID 32580356, 2020). "MAOA and MAOB are crucial target genes of various mental diseases, and MAOA is particularly important in depression and anxiety." (PMID 32182911, 2020). "In this work, we aimed to find potential drugs for PCa patients suffering from depression by establishing novel anti-PCa reversible monoamine oxidase-A inhibitors (MAO-AIs/RIMA); with an endeavor to understand their mechanism of action." (PMID 32403270, 2020). "Presently monoamine oxidase A (MAO-A) is useful in the treatment of depression disorders, because MAO metabolizes serotonin or 5-hydroxytryptamine (5-HT) in the central nervous system (CNS)." (PMID 32899148, 2020). "Monoamine oxidase A inhibitors (MAOAIs), typically used to treat depression have shown to moderate PC growth and inhibit metastasis due to high concentration of MAOA in the prostate." (PMID 31555580, 2019). "MAOA is a critical enzyme that metabolises monoamines including serotonin, norepinephrine and dopamine and shows elevated expression in major depression disorders." (PMID 30956902, 2019). "The 5-hydroxytryptamine (5-HT) system, which includes the 5-HT transporters, 5-HT receptors and monoamine oxidase A (MAO-A), has been used as a drug target in the pharmacotherapeutics for depression." (PMID 30271325, 2018). "Several studies have noted that MAOA is related to the aetiology of different mental illnesses, such as depression." (PMID 29881923, 2018). "A number of situations have been shown to modify the MAOA expression, including Major Depressive Disorder (MDD), stressful events, diet changes, tobacco smoking, and social environment." (PMID 30558545, 2018). "Another study also revealed that women with MAOA and COMT low-activity alleles scored higher for postpartum depression symptoms." (PMID 30018578, 2018). "They found that the genetic variant of the DRD2 gene associated with the anxiety, depression (ANX/DEP) alcoholic phenotype, and the genetic variant of the MAOA gene was associated with alcoholism." (PMID 24878765, 2014). "However, using SEM, we further determined that the MAOA 4R allele might be associated with suicide among patients with depression after controlling for other associated factors, such as gender, age, the personality characteristics of extraversion and neuroticism, and anxiety symptoms." (PMID 21605465, 2011). "The serotonin transporter polymorphism (5HTTLPR) and the monoamine oxidase A polymorphism (MAOA-LPR) have been implicated in conditions and behaviours such as depression, anxiety, aggression, alcoholism, autism, suicidality, and impulsiveness." (PMID 20187845, 2010). "Polymorphisms of the MAOA gene have been used to extensively study its association with several psychiatric conditions, such as BPD, depression, and aggression-related traits." (PMID 18501009, 2008). "Moreover, MAOA upregulation correlates strongly with depressive disorder, while MAO inhibitors effectively ameliorate depressive symptoms." (PMID 41471275, 2025). "Another study on mice with 5% full-thickness burns, showed that mice had increased concentrations and transcription of monoamine oxidase A (MAOA) a week after their burn injuries, which is a neurotransmitter associated with CNS abnormalities related to depression." (PMID 38312739, 2024). "Although not statistically significant, only patients with MAOA uVNTR polymorphism's 3R@ and 3R/4R genotypes (at least one 3R allele) presented cases of severe depression according to the revised Beck Depression Inventory-II (BDI-II) interpretations." (PMID 37533936, 2023).
depression (continued). "Moreover, genetic variations in the monoamine oxidase A (MAOA) associated with reduced amygdala-PFC coupling can predict the course and severity of major depression." (PMID 37898626, 2023). "The study of MAOA epigenetics found that depression may occur when MAOA is subjected to disordered DNA methylation programming, and MAOA-genotypic variants may mediate NR3C1’s metabolism." (PMID 37065890, 2023). "The 4R allele also appeared to indirectly affect suicide attempts associated with depressive symptoms (structural equation modeling, SEM ~ MAOA-depression: b = −0.12, p = 0.031; depression-suicide: b = 0.32, p < 0.001), conferring a vulnerability to suicide in MDD men." (PMID 36291132, 2022). "Moreover, depression would escalate the histological changes in reverse, probably through the monoamine oxidase-A enzyme pathway." (PMID 34983435, 2022). "The dysregulated functions of MAOA in neural signal transmission may lead to depression, autism, or aggressive behavior phenotypes, which may be involved as non-motor psychiatric manifestations of PD." (PMID 33815093, 2021). "Furthermore, analyses of the associations of age and sex with methylation were adjusted for several factors previously related to MAOA, including depression and anxiety disorders, and impulsivity that characterizes individuals with antisocial disorders." (PMID 34424394, 2021). "Moreover, MAOA enzyme and SLC6A4 transporter associated with tryptophan metabolism play key role in mediating activity of HLJDD against depression." (PMID 33746756, 2021). "Prostate cancer patients with a high-grade tumor showed upregulation of MAOA expression; the targeting of anti-depression drugs on MAOA may have potential for use in the therapy of advanced prostate cancer." (PMID 34209963, 2021). "In particular, methylation of MAOA in the promoter region of CpG5 and CpG11 increases MAOA expression, which in turn decreases serotonin levels; this has been observed in female patients with depression." (PMID 33584798, 2020). "Therefore, HR can ameliorate depression symptoms by down-regulating MAOA subsequently elevating serotonin and norepinephrine in the brain." (PMID 32182911, 2020). "In light of the monoamine hypothesis of depression, investigators have studied MAOA DNA methylation and its interaction with antidepressants." (PMID 32012861, 2020). "Similar results were obtained for HTR2A rs6313 and MAOA rs3788862 for anxiety and depression." (PMID 30656852, 2019). "Other studies also found neurobiological changes in mourning that are distinct from changes in depression (e.g., activation of nucleus accumbens, activation of amygdala, variation in the monoamine oxidase A (MAO-A) promoter gene, variation in heart rate variability)." (PMID 29997487, 2018). "Our results show a significant upregulation of MAOA and TAC1 in the medial area frontopolaris which is a node in the limbic-cortical network and known to be susceptible for gray matter loss and behavioral dysfunction in patients with depression." (PMID 29478144, 2018). "The third aim was to determine whether methylation of the MAOA ROI mediates associations of abuse with alcohol dependence, drug dependence, depression disorders, anxiety disorders, and CD." (PMID 29600412, 2018). "In this study, we investigated the difference in orbitofrontal cortex thickness between medication-naïve female patients with major depressive disorder and healthy controls, and the influence of MAOA-uVNTR genotype on orbitofrontal cortex thickness in depression." (PMID 27752275, 2016). "Future studies with larger sample sizes are needed to detect a possible association between MAOA-uVNTR genotype and OFC thickness in depression, which will help investigate the mechanistic hypotheses motivated by our results." (PMID 27752275, 2016).
depression (continued). "In this study, we investigated the effects of MAOA genotype and its interaction with sex and early adversity on different aspects of aggression in young adults, that is, state aggression but also aggression in the context of depression." (PMID 23170243, 2012). "The logistic regression analysis that we carried out confirmed neither a significant association between the MAOA 4R allele and suicide nor an association between the MAOA 4R allele and depression." (PMID 21605465, 2011). "In addition, postmortem results have shown an increased level of MAOA activity in the hypothalamus of the brains of suicide victims with depressive disorder." (PMID 21605465, 2011). "Thus, MAOA, a key enzyme in monoamine metabolism involved in depression, might serve as a common imaging biomarker." (PMID 39201521, 2024). "Therefore, HF may improve depression symptoms by regulating including but not limited to MAOA, MAOB, AR, CAMK2A, and GAD2." (PMID 34306154, 2021). "Hence, targeting the MAOA-related PTGS1 signaling pathway by miR-15b-5p/miR-92b-3p could provide a novel therapeutic avenue for treating OSA-related depression." (PMID 34829725, 2021). "Finally, in patients suffering from severe depression, the administration of a MAOA/MAOB inhibitor along with an oral supplementation with L-phenylalanine was reported to exert beneficial effects via a mechanism presumably involving an increase in brain β-PEA levels." (PMID 34638785, 2021). "Aberrant activity of MAOA has been posited as a critical factor involved in system-wide aminergic dysregulation that, in turn, contributes to the development of multiple negative outcomes including increased aggressive behavior, substance misuse, and mental disorders such as depression." (PMID 34424394, 2021). "However, despite numerous candidate gene studies and GWAS, no MAOA gene has proven associated with depression." (PMID 40761411, 2021). "Extant evidence also implicates gene-by-environment interactions of a functional variable nucleotide polymorphism in the promoter of MAOA (MAOA-uVNTR) and adversity in modifying risk for negative behavioural outcomes, principally antisocial behaviour, and mental disorders such as depression." (PMID 34424394, 2021). "The monoamine oxidase A inhibitor drug harmine was suggested to have both antidepressant and anti-inflammatory properties and may, therefore, be a potential candidate for treatment of depression." (PMID 32088835, 2020). "We analyzed the relationship between the severity of depression according to the BDI and the frequency of the genotypes of the 44-bp VNTR polymorphism in the 5-HTT gene (SLC6A4) promoter region and the 30-bp VNTR polymorphism in the MAO-A gene (MAOA) promoter region." (PMID 33379297, 2020). "Interestingly enough, MAOA is also related to depression in female patients." (PMID 27992373, 2017). "The monoamine oxidase A (MAO-A) gene may be also responsible for an inclination to depression." (PMID 25655492, 2015). "Also, several polymorphisms in MAOA in the non-autosomal portion of the X chromosome appear associated with depression." (PMID 23521777, 2013). "Both MAOA and ASMT may influence melatonin metabolism, with polymorphisms possibly leading to delayed melatonin offset, triggering photoperiodic mechanisms which manifest as depression." (PMID 23521777, 2013). "There are limited studies on the sex differences between MAOA gene variation and ELS inducing depression." (PMID 35663561, 2022). "Important genes involved in neurotransmitter transmission in these pathways include ACHE, MAOA, and DRD2 are related to the development of depression." (PMID 36072347, 2022). "Leu235Val was found to accelerate the monoamine-oxidase-A (MAO-A) production, resulting in lower serotonin and noradrenalin expression, leading to depression." (PMID 36142879, 2022).